BRD4 (bromodomain containing 4)
Diseases named in the same sentence as BRD4 in open-access papers (continued):
Sharing a sentence is not in itself a finding about the gene and the disease.
cancer (continued). "Therefore, to investigate potential functional redundancy between BRD4 and BRDT in BRDT-expressing cancer cells, we decided to assess the impact of BRD4 versus BRDT loss on the transcriptional response to hypoxic stress." (PMID 40085698, 2025). "While an effect on 3’UTR isoform expression was not tested in that study, BRD4 is known to interact with and recruit the cleavage and polyadenylation machinery during transcription elongation and co-inhibition of BRD4 and TOP1 induces readthrough transcription with implications for other cancers." (PMID 40654921, 2025). "Therefore, we aim to develop a novel and effective dual-targeting BRD4/STAT3 inhibitor to avoid the liability arising from monotherapy and combination therapy and provide a new option for cancer treatment." (PMID 40078291, 2025). "JNK activation and BRD4 transcriptional activity are significantly enhanced during cellular stress, immune/inflammatory responses and epithelial to mesenchymal transition (EMT) during cancer progression." (PMID 40970132, 2025). "Although myc expression is generally associated with cancer, HGPS patients do not have an increased incidence of cancer, possibly due to an inherent resistance mechanism mediated by the BRD4 transcription factor." (PMID 41000886, 2025). "Furthermore, BRD4 recruits Mediators and NF-κB p65 to form SEs at TP63, MET, FOSL1, and triggers transcription of cancer stemness genes and pro-metastatic genes in HNSCC." (PMID 39090713, 2024). "Inhibiting the BRD4 BD1 domain has shown promising results in halting this transcriptional misregulation, resulting in the suppression of tumor growth and the induction of apoptosis in cancer cells." (PMID 39458928, 2024). "Whether CHMP5 also regulates AML, in which the BRD4-dependent MYC super-enhancer is also a therapeutic vulnerability, and other cancers that display a p300-BRD4 dependency remains to be determined." (PMID 38352301, 2024). "A novel biomimetic codelivery system (MCM@UN) was constructed by MOF nanoparticles UiO-66 loading with a bromodomain-containing protein 4 (BRD4) inhibitor and then coated with the membrane vesicles of homologous cancer cells that embedding the 18 C lipid tail of 3M-052 (M)." (PMID 38811964, 2024). "In the clinical aspect, BRD4 was also expressed at higher levels in the cancer portion rather than in the normal stomach." (PMID 38540967, 2024). "Upon endocytosis into cancer cells, compound 23 underwent specific internalization and lysosomal trafficking within HER2-positive cells, thereby facilitating the release of the active PROTAC and effectively inducing significant irreversible BRD4 degradation." (PMID 38389844, 2024). "Among the BET family, BRD4 is the best-studied member to regulate tumorigenesis through cancer cell autonomous and non-autonomous mechanisms." (PMID 39872506, 2024). "Inhibition of BRD4 and further BET family members are highly relevant for cancer therapy." (PMID 38233583, 2024). "BRD4’s intricate involvement in DDR, transcription regulation, and cancer biology not only underscores its vital cellular roles but also its potential as a therapeutic target in cancer treatment." (PMID 39066258, 2024). "Brd4, an I-BET target, is known to co-activate NF-κB signaling by interacting with acetylated RelA (p65) to promote its stability and transactivation activity in cancer cells." (PMID 38994961, 2024). "Moreover, since NRF2 by itself is considered an undruggable target, we used a BRD4 inhibitor, I-BET-762, with anti-tumor properties in several cancers to suppress the activation of the NRF2 pathway." (PMID 39337472, 2024). "BRD4 was significantly correlated with abundance of activated CD8 T-cell (Act_CD8; rho = −0.445, p < 0.001), and effector memeory CD4 T-cell (Tem_CD4; rho = −0.496, p < 0.001) of TILs across human heterogeneous cancers." (PMID 36711038, 2023).
cancer (continued). "Bromodomain-containing protein 4 (BRD4), a member of the bromodomain and extra-terminal family (BET), has attracted great attention from academia and the pharmaceutical industry due to its great potential as a new target for a variety of cancers." (PMID 37993451, 2023). "In contrast, Brd4 protein expression was not altered if cancer cells were treated with “pre-prepared” (+)-JQ1-CLIPTAC (10 μM) due to the poor cellular permeability of the PROTAC." (PMID 37049806, 2023). "Regrettably, no BRD4 inhibitors have yet cleared clinical trials to gain approval as cancer chemotherapy agents." (PMID 38099141, 2023). "In fact, it has been shown that BRD4 plays a nontranscriptional role in regulating DNA damage checkpoint activation and repair as well as telomere preservation, shedding new light on’the many roles of BRD4 and providing fresh ideas for the application of BET inhibitors in cancer." (PMID 37501079, 2023). "Additionally, studies indicated that BRD4 is a known trigger of Runt-related transcription factor 2 (RUNX2), and in some cancer cells, RUNX2 is a direct target of BRD4 inhibition by JQ-1." (PMID 37509171, 2023). "Recently, several potent small-molecule BRD4 inhibitors such as JQ1 and I-BET, which disrupt BET proteins binding to acetylated histones, have been discovered and have shown promising therapeutic potential in preclinical models of multiple cancers." (PMID 36733715, 2023). "When combined with the mother chemical ARV-771, the folate PROTAC 10 demonstrated comparable BRD4 degradation in cancer cells compared to non-cancerous normal cells." (PMID 37241755, 2023). "Cancer cells treated with BRD4 inhibitors subsequently suffer not only damage arising from double-strand breaks and R-loop accrual at a subset of BRD4-controlled genes but also mitotic catastrophe, all leading to cell death." (PMID 37108225, 2023). "Upon BRD4/YAP targeting, ROR1 expression is reduced, thereby preventing cancer cell growth." (PMID 37994501, 2023). "Overall, targeting both BRD4 and PLK1 represents a promising strategy for developing novel anticancer therapies, because this dual inhibitor can inhibit multiple processes involving cancer growth and survival." (PMID 37765111, 2023). "As a BRD4 inhibitor, JQ1 has a strong inhibitory effect on a variety of cancers, including PCa, and it has shown great application prospects in the treatment of various cancers." (PMID 37875480, 2023). "BRD4 contains two tandem bromodomains (BD1 and BD2) that recognize acetylated lysine for epigenetic reading, and these bromodomains are promising therapeutic targets for treating various diseases, including cancers." (PMID 37402749, 2023). "BRD4 inhibitors are also widely used to treat a variety of cancer-related and non-related disorders." (PMID 36902175, 2023). "Our study suggests that the BRD4-NUT/p300 bipartite interaction likely plays an important role for propagating histone hyperacetylation, chromatin condensation and sustaining aberrant gene transcription to perpetual tumor cell growth in NC carcinoma." (PMID 36690674, 2023). "In addition, BRD4 can be inhibited together with other epigenetic regulators, such as HDAC, to achieve the best anti-cancer effect." (PMID 36187481, 2022). "Our compounds are active in BRD4-dependent cell lines and had good liver microsomal stability, suggesting these molecules are potential chemical probes to investigate the roles of BET BD1 in cancer models and BRDT-BD1 in in vivo spermatogenesis models." (PMID 35622893, 2022). "To explore the relationship between PRMT2/4-mediated BRD4 methylation and DDR, we induced DNA damage using a topoisomerase II inhibitor, etoposide, which has been used in PRMT1/5-relevant studies and is widely used for cancer treatment." (PMID 36475791, 2022). "Overall, DUB3 stabilizes BRD4 through deubiquitination and promotes cancer progression, suggesting that DUB3 may be an effective anticancer target for cancer therapy." (PMID 35402244, 2022).
cancer (continued). "A more detailed understanding of the molecular mechanisms involving BRD4 and NFAT in T-cell exhaustion may provide opportunities to better understand the effects of BET inhibition in cancer immunotherapy." (PMID 35918330, 2022). "BRD3 may affect cancer prognosis by controlling the expression of oncogenes, such as MYC, in a similar manner to BRD4." (PMID 34605158, 2022). "Notably, the expression levels of both BRD4 and MYC were elevated in HCT116 cancer cells compared with those in the normal colorectal cell line ccd18co." (PMID 35159127, 2022). "As a BRD4 inhibitor, JQ1 blocks the interaction between BRD4 and acetylated histones to suppress gene transcription, and has shown efficacy against many types of cancers." (PMID 35406486, 2022). "BRD4 preferentially binds to super enhancers of growth-stimulating promoters, such as at the oncogene MYC, which may allow cancer cells to be specifically sensitive to BET inhibitor therapy." (PMID 36077617, 2022). "Our recent preclinical studies with the first-generation BTK/PI3K/BRD4 inhibitor SRX3262 in MCL demonstrated reduced phosphorylation of MYC at Ser62 and Thr58, which are critical mediators of MYC protein stability and degradation in cancer." (PMID 35743155, 2022). "Small molecule inhibition of BRD4 (such as JQ1 and BET inhibitors) has been shown to reduce cell proliferation and survival in vivo as well as increase therapeutic sensitivity of several cancer types, leading to the development of several clinical trials." (PMID 35869079, 2022). "With the observation that BET proteins are upregulated in cancer and facilitate transcription of oncogenes such as c-MYC, this led to the concept that BET proteins, particularly BRD4, facilitate tumorigenesis via transcriptional coactivation of oncogenes." (PMID 35467128, 2022). "In line with the efficiency of our system in down-regulating the hypoxia-responsive proteins including VEGF in cancer cells and its ability to reduce HIF-1α level via BRD4 depletion in zebrafish, we next evaluated the ENCTAC capacity in modulating angiogenesis, one typical hallmark of tumors." (PMID 36516252, 2022). "BRD4, a member of the bromodomain and extraterminal (BET) family, plays transcriptional and epigenetic regulatory roles in embryogenesis, apoptosis, and inflammatory response, particularly in cancer development." (PMID 36352160, 2022). "BRD4, a member of the bromodomain and extra-terminal domain (BET) family, plays a crucial role in the development of multiple cancers and is regarded as a novel cancer therapeutic target." (PMID 35164758, 2022). "Recent evidence suggests that BRD4 has additional non-transcriptional functions in cancer, affecting processes such as DNA damage repair, checkpoint activation, or telomere homeostasis." (PMID 36524001, 2022). "In HR-proficient cancers, induction of synthetic lethality can be achieved through HRR inhibition by using specific inhibitors of ATM, ATR, Topoisomerase 2 or Bromodomain Containing 4 (BRD4) to create a BRCAness phenotype." (PMID 35328658, 2022). "As expected, the resultingAPC 13 (entry 13) showed comparable BRD4 degradation with the parentalPROTAC (APC 13, DC50 = 22 nM, Dmax > 90% vs parental PROTAC DC50 = 13 nM, Dmax > 90%) in highly nucleolin-expressingMCF-7breast cancer cells." (PMID 36110375, 2022). "Further studies should expand to establish a role for EGFR/BRD4/miR-9-5p axis in tumour itself and tumour microenvironment towards the development of better, less toxic and more efficient therapeutics for HPV-infected cancers." (PMID 36333293, 2022). "Accumulating research has found that apoptosis is not the only type of death induced by Brd4 inhibition, autophagy, pyroptosis or ferroptosis is also involved in Brd4 inhibition-induced cancer cell death." (PMID 36539410, 2022).
cancer (continued). "BRD4, a member of the bromodomain and extraterminal (BET) protein family, is a master transcriptional and epigenetic regulator that plays a pivotal role during several processes from embryogenesis to cancer development." (PMID 34417184, 2021). "The development of JQ1 offered a great opportunity to better understand the biology of BET proteins, validate the oncogenicity of BRD4 and to determine whether BET proteins are bona fide anti-cancer targets." (PMID 33723398, 2021). "Indeed, several studies proposed that the depletion or pharmacological inhibition of BRD4 directly impacted the expression of HR genes, such as RAD51, BRCA1 and BRIP1, and enhanced the sensitivity of cancer cells to PARP inhibitors." (PMID 34208195, 2021). "Overall, this demonstrates that the mechanism of resistance to BETi varies depending on cancer type, with LAC cells developing JQ1 resistance independent of MYC regulation, and identifying CK2 phosphorylation of BRD4 as a potential target to overcome resistance in this cancer." (PMID 33712563, 2021). "This approach identified many confirmed targets with existing drugs that are currently used in the clinic or are in various stages of clinical trials in other cancers (for example clinical trials for drugs targeting AURKA and BRD4), emphasizing the efficacy of our approach." (PMID 34154646, 2021). "Accordingly, BRD4 inhibition impairs CDK9 recruitment to MYC, reduces MYC transcripts levels, down-regulates Myc-dependent target genes, and has anti-proliferative effects in cancer cells." (PMID 34146121, 2021). "BRD4 and RAC1 oncoproteins play important roles in cancer cell growth, migration, invasion and metastasis, hence the focus on these two oncogenes as potential therapeutic targets in different cancers 23,50,51." (PMID 34803511, 2021). "Similarly, in this study, higher mRNA and protein expressions of BRD4 were found in HCC, and mRNA expression of BRD4 was significantly correlated with cancer stages and tumor grades." (PMID 32927435, 2020). "When combining JQ1 with a PI3K inhibitor, or using the double PI3K/BRD4 inhibitor SF2523 (previously reported as a strong inhibitor of tumor growth and metastasis in various cancer models), tumor growth was suppressed in syngenic and spontaneous mouse cancer models." (PMID 32486098, 2020). "It has been proved that BRD4 is overexpressed in many types of cancers and is a negative predictor of cancer survival." (PMID 32954665, 2020). "BRD4, a member of the BET protein family, amplifies oncogenic transcription by recruiting transcriptional machinery or indirectly by binding to enhancers, contributing to cancer cell proliferation and survival." (PMID 32184777, 2020). "BRD4, a member of the bromodomain and Extraterminal (BET) protein family, is a transcriptional and epigenetic regulator playing an essential role during embryogenesis and cancer development." (PMID 32824207, 2020). "BRD4 is the most abundant and important BET family protein in cancer cells." (PMID 32163373, 2020). "Oncogenes, such as MYC, have a transcriptional dependency on BRD4 and recent findings suggest additional non-transcriptional functions of BRD4 in cancer." (PMID 33322239, 2020). "In contrast, simultaneous targeting of multiple pathological pathways, implicating both BDs of BRD4 and additional cancer drivers such as PI3K and/or CDK4/6 notably increases efficacy." (PMID 32694708, 2020). "BRD4 and CDK7 are essential components of SEs in various cancers." (PMID 33298918, 2020). "While original functional and genomic studies on BRD4 were performed on NUT midline carcinoma, because of the lower incidence of this disease (as compared to other cancers), diverse scientific opinions exist on a more generalized applicability in other malignancies." (PMID 32218352, 2020).
cancer (continued). "The Bromodomain and Extraterminal Domain (BET) gene family, including BRD2, BRD3, BRD4, are so-called “histone readers” of lysine acetylation of the N-terminal part of histone and involved in regulating sensitivity to MAPK inhibition in a number of cancers." (PMID 32046099, 2020). "BRD4 and CDK7 inhibitors JQ1 and THZ1 can kill many different cancer cells." (PMID 33298918, 2020). "Knockdown of BRD4 or BET inhibitors are known to demonstrate strong antitumour activity by inducing cell cycle arrest, apoptosis, differentiation and metastasis of various cancer cells." (PMID 32954665, 2020). "The results showed that BRD4 expression levels were higher in cancer tissues than in normal tissues and were related to poor prognosis in cancer patients." (PMID 30988278, 2019). "As an example, BRD4-NUT translocation is the primary determinant of NMC, in which BRD4 protein to the NUT transcriptional regulator drives the expression of BRD4, promoting transcription of cancer progression-related genes." (PMID 30634442, 2019). "Furthermore, BRD4 expression was positively related to GPX4, SLC7A11, and SLC3A2 expression in pan-cancer patients." (PMID 30988278, 2019). "Recent evidence adds further complexity on the role of BRD4 in cancer, showing that this protein plays additional non-transcriptional functions, affecting processes like DNA damage repair and checkpoint activation or telomere homeostasis." (PMID 30466442, 2018). "Particularly, BRD4 is required for the expression of MYC, an oncogenic driver in many cancers." (PMID 30304769, 2018). "In conclusion, BRD4 expression may be a potential prognostic marker in ccRCC, and JQ1, as a BRD4 inhibitor, significantly inhibited cancer cell aggressiveness both in vitro and in vivo in sunitinib-sensitive and -resistant ccRCC." (PMID 29796168, 2018). "Cancer cells are more sensitive to treatment with small-molecule inhibitors of CDK7 or BRD4 than non-transformed cells." (PMID 29724031, 2018). "BRD4, one of the BET (bromodomain and extra-terminal) family proteins, has become a key player in transcription, cell cycle control, inflammatory cytokine production and cancer development." (PMID 29434197, 2018). "Several previous studies demonstrated that BRD4 could regulate MYC gene transcription and that JQ1 effectively suppresses cancer cell proliferation by inhibiting BET-mediated regulation of MYC in various types of cancer." (PMID 29796168, 2018). "Taken together, our present data suggested that BRD4 inhibition by JQ1 in patients with sunitinib-sensitive and -resistant ccRCC may improve their prognosis and suppress cancer progression by comprehensively suppressing the expression of these oncogenes." (PMID 29796168, 2018). "Consequently, BRD4 inhibitors, such as JQ1 and I-BET, have been demonstrated to be effective suppressors of inflammation in treating various cancers and inflammatory diseases." (PMID 30029633, 2018). "Recently, bromodomain containing 4 (BRD4), a member of the bromodomain family proteins, was identified as a promising therapeutic target, and its inhibitor JQ1 has been shown to have inhibitory effects in various human cancers." (PMID 29796168, 2018). "Considered the centrality and the multifunctional role that BRD4 plays in transcription regulation it is not surprising that BETi represent an attracting strategy in cancer therapy." (PMID 30466442, 2018). "Here we discuss the current available information on non-canonical, non-transcriptional functions of BRD4 and on their implications in cancer biology." (PMID 30466442, 2018). "Recent studies have demonstrated that epigenetic regulators are becoming new therapeutic targets for cancer therapy, of which as a member of the bromodomain and extraterminal domain (BET) proteins, bromodomain-containing protein 4 (BRD4) has been widely investigated." (PMID 28545522, 2017).